AKR1B10 (aldo-keto reductase family 1 member B10)
Diseases named in the same sentence as AKR1B10 in open-access papers (continued):
Sharing a sentence is not in itself a finding about the gene and the disease.
breast carcinoma (41 papers, 2000 to 2025). "AKR1B10 encodes a multifunctional NADPH-dependent reductase that stimulates BT-20 breast cancer cell growth in vitro and metastasis in vivo." (PMID 38600165, 2024). "Recently, AKR1B10 was also implicated in promoting the progression of primary lung cancer and conferring resistance to cisplatin, anthracycline in breast cancer, and doxorubicin in gastric cancer." (PMID 39001490, 2024). "Next, the association between AKR1B10 expression and clinicopathological characteristics of patients with breast cancer (n = 63) was analyzed." (PMID 34419144, 2021). "In patients with breast cancer, elevated AKR1B10 expression is also associated with chemotherapy drug resistance." (PMID 34419144, 2021). "Based on these findings, we comprehensively investigated the effects of AKR1B10 and its associated mechanisms in breast cancer with the goal of developing a novel foundation for future breast cancer diagnosis and treatment." (PMID 34419144, 2021). "The findings raise the opportunity to use AKR1B10 expression to identify breast cancer patients with an increased risk of distant metastatic relapse, and further develop AKR1B1023 and FAO32 inhibitors in the advanced breast cancer setting." (PMID 31221959, 2019). "In this study, we investigated the potential involvement of ERK signaling pathway in AKR1B10-associated breast cancer cell migration and invasion in vitro." (PMID 28402270, 2017). "Similarly, in individuals with breast cancer, elevated levels of AKR1B10 are linked to resistance to chemotherapy drugs." (PMID 38931461, 2024). "Aldo-keto reductase 1B10 level is high in non-gastrointestinal solid tumors like liver cancer, lung cancer, breast cancer, and oral squamous cell carcinoma, while it is decreased in colorectal cancer, which may be caused by the tissue specificity of AKR1B10." (PMID 37823316, 2023). "We further estimated the potential diagnostic value of the serum AKR1B10 in breast cancer." (PMID 35280770, 2022). "However, little is known about the detailed function and underlying molecular mechanism of AKR1B10 in the pathological process of breast cancer." (PMID 34419144, 2021). "A further example is represented by AKR1B10, encoding an aldose reductase involved in the reduction of biogenic and xenobiotic aldehydes and whose altered expression has been reported in doxorubicin resistant breast cancer cells." (PMID 33863935, 2021). "However, little is known about the detailed function and underlying molecular mechanism of AKR1B10 in the pathology of breast cancer." (PMID 34419144, 2021). "This was also observed in lung and breast cancers suggesting that AKR1B10 overexpression could be associated with a broader tumor phenotype." (PMID 22876234, 2012). "Given its ability to differentiate high and low Stage I disease, we think that AKR1B10 may be a protein whose expression in breast cancer tissues can further categorize this intermediate risk group of breast cancer patients and aid the clinician in the decision to administer chemotherapy." (PMID 35280770, 2022). "AKR1B10 behaves as a metastasis enhancer in breast cancer via its ability to promote fatty acid oxidation, although high expression was only associated with poor distant metastasis free survival in ER- and HER2 + breast cancer, not in ER + breast cancer." (PMID 40597443, 2025). "A growing body of literature has revealed the dysregulated AKR1B10 expression in a wide range of human malignancies, such as breast cancer, gastric cancer, colon cancer, and so on." (PMID 38671310, 2024). "In breast cancer, AKR1B10 also promotes cell invasion and metastasis through stimulation of the FAK/Src/Rac1 signaling pathway." (PMID 38370384, 2024). "AKR1B10 was reported to be upregulated in liver cancer, lung cancer, breast cancer, oral cancer, pancreatic cancer, cervical cancer and papillary renal cell carcinoma." (PMID 39712017, 2024).
breast carcinoma (continued). "A positive correlation was seen between high levels of AKR1B10 in serum and tumor tissues in breast cancer patients." (PMID 39055885, 2024). "Silencing of AKR1B10 inhibited cell growth rate in BT-20 human breast cancer cells and suppressed tumor development in female nude mice." (PMID 39055885, 2024). "As for prognostic values, AKR1B10 expression was reported to be correlated with poor prognosis in liver cancer, oral cancer, breast cancer, lung cancer, but with favored prognosis in CRC." (PMID 39712017, 2024). "AKR1B10 expression is elevated and correlated with poor prognosis in several types of cancers like hepatocellular carcinoma, breast carcinoma, lung cancer and oral cancer, but is quite opposite in colorectal cancer." (PMID 39712017, 2024). "Qu et al18 reported that AKR1B10 was substantially upregulated in breast cancer tissues, and it facilitated cell malignant phenotypes via modulation of Phosphoinositide 3-kinase/Protein Kinase B/Nuclear factor kappa-B (PI3K/AKT/NF-κB) signaling pathway." (PMID 37823316, 2023). "More interestingly, AKR1B10 is found to promote tumor growth in the metastatic sites and distant relapse of breast cancer through inhibition of the oxidative lesions derived from fatty acid oxidation." (PMID 35280770, 2022). "We also evaluated the diagnostic values of the serum AKR1B10, and our data suggested the potential of serum AKR1B10 as a novel biomarker of breast cancer." (PMID 35280770, 2022). "In breast cancer, AKR1B10 protein is overexpressed in primary, metastatic, and recurrent diseases; AKR1B10 was also found to be upregulated in ductal carcinoma in situ (DCIS) (71.4%, n=28)." (PMID 35280770, 2022). "Recently, it has been found that AKR1B10 is a secretory protein and is secreted through a secretory lysosome-mediated non-classical pathway, thus being a potential serum biomarker of breast cancer." (PMID 35280770, 2022). "Our data exhibited that AKR1B10 was highly expressed (scored at 3) in 7 (21.9%) of 32 breast cancer tissues, moderately expressed (scored at 2) in 5 (15.6%) cases, and expressed at a low level (scored at 1) in 9 (28.1%) cases." (PMID 35280770, 2022). "Aberrant expression of Aldo-Keto reductase family 1 member B10 (AKR1B10) was associated with tumor size and metastasis of breast cancer in our published preliminary studies." (PMID 34419144, 2021). "Taken together, we show that AKR1B10 regulates different genes known to regulate breast cancer proliferation, migration and invasion." (PMID 34419144, 2021). "The clinicopathological correlation analysis indicates a role for AKR1B10 in the proliferation and metastasis of breast cancer cells." (PMID 34419144, 2021). "Previous studies suggest that PIP2 is upregulated in breast cancer cells in which AKR1B10 is overexpressed, which prompted us to investigate the phosphatidylinositol and PI3K/AKT pathway in detail." (PMID 34419144, 2021). "Studies suggested that AKR1B10 is a new biomarker for cancer based on its overexpression in epithelial tumors, such as breast cancer, cervical cancer, and lung cancer." (PMID 34521883, 2021). "The expression levels of AKR1B10 were detected and compared in the breast cancer cell lines and tissues by RT-qPCR, western blot and immunohistochemistry." (PMID 34419144, 2021). "We analyzed AKR1B10 mRNA and protein levels in 30 pairs of fresh breast cancer tissue/normal tissue by qRT-PCR and western blotting." (PMID 34419144, 2021). "Consistently, our study demonstrated that the PI3K/AKT pathway was upregulated in AKR1B10-induced breast cancer progression." (PMID 34419144, 2021). "In vivo tumor xenograft experiments were used to observe the role of AKR1B10 in breast cancer growth in mice." (PMID 34419144, 2021). "This suggests that high expression levels of AKR1B10 in tumors are closely related to the proliferation of breast cancer cells." (PMID 34419144, 2021).
breast carcinoma (continued). "We examined changes in the expression levels of the EMT-related proteins ZEB1, SNAI1, SLUG, Twist and E-cadherin after AKR1B10-gene intervention in the breast cancer cells by western blot." (PMID 34419144, 2021). "Another recent study found that AKR1B10 can promote proliferation and migration/invasion of breast cancer cells via the ERK and FAK/Src/Rac1 signaling pathway." (PMID 34419144, 2021). "Meanwhile, AKR1B10–ERK signaling had been reported to be involved in the tumor aggressiveness in breast cancer and lung adenocarcinoma." (PMID 34035231, 2021). "Although AKR1B10 is upregulated in oral squamous cell carcinoma, breast cancer, cervical cancer, and lung cancer, the relationships of AKR1B10 expression with tumor size, lymph node metastasis, and squamous cell carcinoma differentiation are different." (PMID 34521883, 2021). "In the present study, we show that overexpression of AKR1B10 enhances migration and invasion of breast cancer cells in vitro, while knockdown decreases cell dispersion." (PMID 34419144, 2021). "The relationship between elevated AKR1B10 expression and the overall survival and disease-free survival of breast cancer patients was analyzed by Kaplan–Meier Plotter database." (PMID 34419144, 2021). "To further study the biological function of AKR1B10 in breast cancer, we first established stable breast cancer cell lines overexpressing AKR1B10 in MCF-7 cells by lentiviral infection." (PMID 34419144, 2021). "These in vitro results demonstrated that AKR1B10 not only affects cell proliferation but also promotes migration and invasion in breast cancer cells." (PMID 34419144, 2021). "Our study demonstrates that elevated expression levels of AKR1B10 in breast cancer tissues correlates with lymph node metastasis, tumor size and poor prognosis." (PMID 34419144, 2021). "Aldo-keto reductase family 1 member B10 (AKR1B10) is a novel secretory protein that is overexpressed in multiple tumors, including lung cancer, breast cancer, and colorectal cancer, and is a potential diagnostic and prognostic biomarker for HCC." (PMID 32923383, 2020). "For example, an interesting recent report linked elevated aldo-keto reductase AKR1B10 expression in ER− and HER2+ breast cancers with an increased incidence of metastatic relapse at secondary sites that was associated with increased fatty acid utilization." (PMID 31551501, 2019). "It has been reported that AKR1B10 stimulates breast cancer cell migration and invasion by activating ERK signaling." (PMID 30692511, 2019). "In conclusion, the experimental and clinical data presented support a role for AKR1B10 in promoting metastasis of breast cancers functioning to support an altered metabolic programme during secondary site colonisation." (PMID 31221959, 2019). "In breast carcinoma, AKR1B10 promotes the migration and invasion of neoplastic cells by stimulating ERK signaling." (PMID 30320113, 2018). "Overexpression of AKR1B10 is an initial event in the carcinogenesis of lung, liver, pancreatic, and breast cancer." (PMID 30320113, 2018). "Aldo-keto reductase family 1, member B10 (AKR1B10), is known to be significantly induced in the cells of various cancers such as breast cancer." (PMID 28402270, 2017). "This study also demonstrated that AKR1B10 promotes breast cancer cell invasion and migration via the ERK axis pathway." (PMID 28402270, 2017). "In breast cancer, AKR1B10 is upregulated in the metastatic (78.0%) and recurrent (87.5%) tumors in breast cancer patients in USA, indicating its potential role in breast cancer metastasis and recurrence." (PMID 28402270, 2017). "In the present study, we demonstrated the potential role and mechanism of AKR1B10 in the invasion and migration of breast cancer cells." (PMID 28402270, 2017). "This study demonstrated that AKR1B10 promotes breast cancer metastasis at the cell levels in vitro and ex vivo clinical data." (PMID 28402270, 2017).
breast carcinoma (continued). "This study demonstrated that AKR1B10 promotes breast cancer cell invasion and migration though activation of the ERK signaling pathway." (PMID 28402270, 2017). "AKR1B10 is overexpressed in breast cancer, and promotes the migration and invasion of MCF-7 and BT-20 cells by activating ERK signaling pathway." (PMID 28402270, 2017). "Expression levels of AKR1B10 were scored on the staining intensities from 0 to 3+, and its expression was detected in breast cancer tissue and para-cancerous tissue." (PMID 28402270, 2017). "We detected the AKR1B10 expression in breast cancer patients in China, and also analyzed the internal relation between AKR1B10 expression and the clinic pathological parameters of breast cancer." (PMID 28402270, 2017). "In our study, we demonstrated that ectopic expression of AKR1B10 promoted breast cancer cell migration and invasion through activation of ERK signaling pathway and up-regulation of expression of MMP2, and vimentin." (PMID 28402270, 2017). "In contrast, silencing of AKR1B10 in breast cancer cells BT-20 markedly lowered down their adhesion to fibronectin or collagen-coated plates, but not to laminin or gelatin-coated plates." (PMID 27248472, 2016). "This study also demonstrated that AKR1B10 promotes breast cancer metastasis through activation of the integrin α5 and δ-catenin mediated FAK/Src/Rac1 signaling cascade, in which the integrin α5 and δ-catenin function synergistically." (PMID 27248472, 2016). "AKR1B10, integrin α5 and δ-catenin were upregulated in breast cancers, particularly in the metastatic lymph nodes." (PMID 27248472, 2016). "To evaluate translational relevance of the study results, we further investigated the expression and correlations of AKR1B10, integrin α5 and δ-catenin in human breast cancer tissues using adjacent sections of tissue microarrays." (PMID 27248472, 2016). "This discovery defines AKR1B10 as a new oncogenic factor in the growth and progression of breast cancer." (PMID 27248472, 2016). "In breast cancer, AKR1B10 is also upregulated in the metastatic (78.0%) and recurrent (87.5%) tumors, indicating its potential role in breast cancer metastasis and recurrence." (PMID 27248472, 2016). "The promoting role of AKR1B10 in breast cancer metastasis was further confirmed in in vivo animal modeling and ex vivo clinical samples." (PMID 27248472, 2016). "Ectopic expression of AKR1B10 in breast cancer cells promoted their adhesion to fibronectin and collagen, migration in fibronectin-coated plates and invasion in Matrigel." (PMID 27248472, 2016). "The current study demonstrated that ectopic expression of AKR1B10 in breast cancer cells MCF-7 enhanced cell adhesion to fibronectin or collagen-coated plates, but not to gelatin or laminin-coated plates." (PMID 27248472, 2016). "In clinical specimens of breast cancer, we observed a high correlation in expression between AKR1B10 and integrin α5 and δ-catenin, being supportive to our mechanistic studies in cell culture." (PMID 27248472, 2016). "In summary, this study demonstrated that AKR1B10 promotes breast cancer metastasis at the levels of in vitro cell culture, in vivo animal and ex vivo clinical settings." (PMID 27248472, 2016). "Our results suggest that AKR1B10 is a new oncogenic factor in breast cancer metastasis and a potential target for metastatic intervention." (PMID 27248472, 2016). "This study demonstrated for the first time that AKR1B10 promoted breast cancer metastasis through activation of the integrin α5 and δ-catenin mediated FAK/Src/Rac1 signaling pathway." (PMID 27248472, 2016). "Nevertheless, AKR1B10 consistently upregulates the expression of δ-catenin and integrin α5 in all tested breast cancer cells." (PMID 27248472, 2016). "This study clarified the molecular mechanism of action that AKR1B10 promotes breast cancer metastasis." (PMID 27248472, 2016).
breast carcinoma (continued). "To confirm the in vitro data that AKR1B10 promotes migration and invasion of breast cancer cells, we extended this study to animals." (PMID 27248472, 2016). "How do integrin α5 and δ-catenin mediate the AKR1B10-promoted adhesion and migration of breast cancer cells then?" (PMID 27248472, 2016). "AKR1B10 is highly expressed in variety of solid tumors such as liver cancer, non-small cell lung cancer, breast cancer, and pancreatic cancer." (PMID 26949513, 2016). "AKR1B10 is overexpressed in distinct types of malignancies, including lung carcinoma, uterine carcinoma, cholangiocarcinomas as well as breast cancer." (PMID 26516929, 2015). "AKR1B10 is a secreted factor and can potentially serve as a prognostic serum marker for breast cancer." (PMID 26516929, 2015). "Aldo-keto reductase family 1 B10 (AKR1B10) is an enzyme overexpressed in multiple cancers including lung, pancreas, liver, uterine, and breast cancer." (PMID 22912720, 2012). "Serum AKR1B10 is regarded as a novel prognostic marker for breast cancer." (PMID 39055885, 2024). "In breast cancer cells, AKR1B10 expression enhances cellular levels of important lipid second messengers, such as phosphatidylinositol bisphosphate (PIP2), diacylglycerol (DAG) and inositol triphosphate (IP3), and thus activates PKC/ERK signaling cascade, promoting tumor growth." (PMID 38370384, 2024). "Moreover, AKR1B10 positively correlated with tumor size, lymph node metastasis, and clinical outcome in breast cancer." (PMID 36661656, 2022). "If true, the serum AKR1B10 may be a promising marker to identify early metastasis of breast cancer, and further study is warranted." (PMID 35280770, 2022). "In addition, the serum AKR1B10 was higher in patients with breast cancer than in the healthy cohort." (PMID 36661656, 2022). "Aldo-keto reductase 1B10 (AKR1B10) is a secretory protein that is upregulated in breast cancer." (PMID 35280770, 2022). "AKR1B10 also appeared to be elevated in all subtypes of breast cancer." (PMID 35280770, 2022). "In liver, lung, and breast cancers, AKR1B10 may be upregulated through the activation of stress-induced signal transduction pathways (such as Nrf2, AP-1, and MAPK pathways) and related to the proliferation and migration of cancer cells." (PMID 34063865, 2021). "It is notable that AKR1B10 expression in human breast cancers positively correlated with PPARGC1A." (PMID 34217300, 2021). "In our previous study, we showed that PI3K inhibitors block cell proliferation of breast cancer cells overexpressing AKR1B10, which suggested that AKR1B10 may regulate the AKT signaling pathway in breast cancer." (PMID 34419144, 2021). "Taken together, these results indicate that AKR1B10 may play an important role in breast cancer development and pathology." (PMID 34419144, 2021). "Taken together, AKR1B10 may affect several signaling pathways related to cell proliferation and migration in breast cancer." (PMID 34419144, 2021). "Interestingly, among DEGs, a relevant number of genes involved in oxidative metabolism (e.g. GSTP1, CYP4Z1, AKR1B10) and in different pathways affecting breast cancer behavior (WNT5A), was observed." (PMID 33863935, 2021). "In our study, we found that AKR1B10 is highly expressed in breast cancer tissue." (PMID 34419144, 2021). "In addition, studies revealed that AKR1B10 is overexpressed in breast cancer, oral squamous cell carcinoma, cervical cancer, and other tumors and is associated with prognosis." (PMID 34521883, 2021). "Notably, AKR1B10 expression is significant in breast cancers that are positive for human epidermal growth-factor receptor type 2 (HER2)." (PMID 34063865, 2021). "AKR1B10 mRNA levels were significantly higher in breast cancer tissues compared to normal tissues." (PMID 34419144, 2021). "Hence, we examined the phosphorylation status of both IKBα and NF-κB p65 in breast cancer cells with AKR1B10 knockdown or overexpression." (PMID 34419144, 2021).